C16orf95 (chromosome 16 open reading frame 95)
Tractability: No criterion of Open Targets' tractability assessment is met for any kind of drug.
Gene: Protein-coding gene on chromosome 16 (87,083,562 to 87,317,420, reverse strand). Ensembl gene ENSG00000260456.
Subcellular location (Human Protein Atlas): Endoplasmic reticulum
Genetic constraint (gnomAD): Loss-of-function variants: 41 observed, 31.32 expected, observed/expected ratio (o/e) 1.31, 90% interval 1.02 to 1.69. The upper end of that interval is the gene's LOEUF score, 1.69, which puts it in group 6 of 6, group 1 being the genes least tolerant of losing a copy. Missense variants: 399 observed, 315.36 expected, observed/expected ratio (o/e) 1.27, 90% interval 1.16 to 1.37. Synonymous variants: 147 observed, 124.91 expected, observed/expected ratio (o/e) 1.18, 90% interval 1.03 to 1.35.
Homologues: Orthologues: chimpanzee C16H16orf95 (95% identical), macaque C16orf95 (85% identical), rat C19h16orf95 (43% identical), mouse 1700018B08Rik (39% identical).
Diseases named in the same sentence as C16orf95 in open-access papers:
C16orf95 is named in the same sentence as 3 diseases in open-access papers, as found by Europe PMC text mining. Sharing a sentence is not in itself a finding about the gene and the disease. The quoted sentences say what the papers report.
breast carcinoma (1 paper, 2020). "The relatively specific lincRNA RP11-65L19.4 gene mutation in the ectoderm group occurred only in four breast cancer cases and two skin cancer cases; PPP1R2P9 AP00345.1 and C16orf95 genes in the mesoderm group mainly existed in the cases with uterus tumors." (PMID 33308219, 2020).
C16orf95 also shares sentences with these, for which no sentence is quoted: skin cancer (1 paper); uterus tumors (1).